CD274 (CD274 molecule)
Diseases named in the same sentence as CD274 in open-access papers (continued):
Sharing a sentence is not in itself a finding about the gene and the disease.
glioma (continued). "In addition, as the expression of NUP37 was highly positively correlated with the genes encoding PD‐L1 (CD274) and PD‐L2 (PDCD1LG2), it is more importantly that PD‐L1 and PD‐L2 are an immune checkpoint inhibitor in gliomas." (PMID 34264013, 2021). "Likewise, MES glioma showed a higher expression of CD274 (PD-L1), which was consistent with TCGA." (PMID 36276655, 2022). "Significant Log2HR values reveal the association of higher CD274 expression with worse survival for skin cutaneous melanoma (SKCM), kidney renal clear-cell carcinoma (KIRC), and adrenocortical carcinoma (ACC), while there is a better patient outcome for low-grade glioma (LGG)." (PMID 36354714, 2022). "The PD-L1/PD-1 axis (CD274/PDCD1) and CTLA4 are currently considered core targets in glioma immunotherapy." (PMID 40661083, 2025). "Thus, the TNFRSF18 and CD274 may have a great potential in the tumor immunotherapy of glioma." (PMID 40351420, 2025). "In our in-house cohort, the expression levels of CD274, HMGB2, RAC2, RIN3, and SOD3 were elevated in WHO grade IV gliomas compared to grades II/III." (PMID 40852729, 2025). "In gliomas, TMED9 correlates with immune cell infiltration (e.g., B cells, T cells) and immune checkpoints like CD274 (PD-L1), suggesting a role in immune evasion." (PMID 41373732, 2025). "Assessments of the immune blockade response to 3 checkpoints (PDCD1, CD274, and PDCD1LG2) and the IC50 for 2 classical antitumor drugs were conducted for glioma samples with varying SOCS1 expression levels in the CGGA and TCGA databases." (PMID 39654174, 2024). "Our data revealed a significant correlation between the expression levels of immune checkpoint molecules (CD274, CTLA4, HAVCR2, LAG3, PDCD1, PDCD1LG2, TIGIT, and SIGLEC15) and RAB32 in high-grade gliomas (HGG)." (PMID 39668831, 2024). "The expression of the more well-known immune-related targets in glioma, such as CTLA4, PDCD1 (PD-1), CD274 (PD-L1), LAG-3, and CD47, was then examined." (PMID 38396140, 2024). "We also found that the HIS subtype had the highest expression of several immune checkpoints (particularly IDO1, CD274 and PDCD1LG2), it means that glioma samples from HIS subtype tend to be immunosuppressed." (PMID 38613347, 2024). "The expression of PD‐L1 (the protein encoded by CD274) was upregulated with the increase in the degree of malignancy of patients, suggesting that the malignant phenotype of glioma patients may be caused by the increased expression of PD‐L1, which promotes immune evasion." (PMID 37786553, 2023). "We found that cluster 2 had a remarkably high expression level of most of the immune checkpoints including PD-1 (PDCD1), PD-L1 (CD274), and CTLA-4 (CD276), and most of these trends were consistent between IDH-mutant and IDH-wildtype gliomas." (PMID 36970537, 2023). "Notably, gliomas in the high-GRMS subgroup exhibited abundant tumor-infiltrating lymphocytes and tumor mutation burden values, increased expressive levels of hepatitis A virus cellular receptor 2 and CD274, and improved progression-free survival when subjected to anti-tumor immunotherapy." (PMID 37663248, 2023). "In glioma cells, the direct binding between HIF-1α and CD274 promoter region results in elevated PD-L1 expression under hypoxia." (PMID 36747292, 2023). "We further analyzed the expression distribution of immune checkpoints gene (including CD274, CTLA4, HAVCR2, LAG3, PDCD1, PDCD1LG2, TIGIT, and SIGLEC15) in glioma tissues and normal brain tissues using the TCGA database." (PMID 36915038, 2023). "We further explored the relationship between ITGA5 and some immune checkpoints, such as PDCD1 (PD-1), CD274 (PD-L1), and PDCD1LG2 (PD-L2) in gliomas based on the TCGA dataset." (PMID 35371978, 2022). "Based on the TCGA and CGGA datasets, we proved that PTX3 positively correlated with CD276, CD274, PDCDL1LG2, HAVCR2, CD80, IDO1, and PDCD1 in pan‐glioma, GBM, and LGG." (PMID 35855654, 2022).
glioma (continued). "In our research, PTX3 is highly correlated with PD‐1, PD‐L1, CD274, CD276, and HAVCR2, all of which can mediate immune escape of gliomas." (PMID 35855654, 2022). "We investigated the immune checkpoint expression in glioma specimens and uncovered that CD274 (PD-L1), PDCD1, PDCD1LG2, CTLA4, CD276, HAVCR2, and LAG3 were significantly overexpressed in the high DDR score subtype." (PMID 35720326, 2022). "The expression levels of PDL1 (CD274), FOXO1, and PRDM1 in the high-HIF1A-expression group were significantly higher in both glioblastoma (GBM) and lower-grade glioma." (PMID 34305618, 2021). "To our surprise, we found that CD44+ T cells express both CD274 (namely PD-L1) and PDCD1 (namely PD-1) in glioma." (PMID 35187044, 2021). "PDIA3 was highly positively correlated with HAVCR2, CD274, PDCD1LG2 and others in pan-gliomas and LGG and GBM samples, and PDIA3 demonstrated a high positive correlation with PDCD1LG2 in GBM." (PMID 32687065, 2020). "Although certain immune checkpoints, including CD274 (PD-L1), PDCD1 (PD-1), and CTLA-4, have been effectively employed in targeted immunotherapy for other organ tumors, this study explored that the expression of these molecules was notably low in gliomas." (PMID 38956740, 2024). "However, MAPKAPK2 is positively correlated with a series of immune regulators such as CD274, CD276, PDCD1, and CD70, which probably affect the tumor killing effect of the infiltrated immune cells in glioma tissue." (PMID 38322416, 2024). "Indeed, the expression of A3C displayed positive correlations with CD274, PDCD1, PDCD1LG2, SIGLEC15, CTLA4, HAVCR2, and GZMB in glioma (P < 0.05)." (PMID 37809064, 2023). "Correspondingly, it showed that CD101 expression could potentially interact with numerous immune-relevant genes, including CD276, CD274, CD80, CTLA4, and PDCD1, implying an immunoregulatory role of CD101 in the glioma immune microenvironment." (PMID 35350788, 2022). "However, the single cell RNA sequencing results showed that CD274 and PDCD1LG2 were not only expressed in malignant cells, but were also heavily expressed in immune cells in gliomas." (PMID 34100771, 2021). "Thus, we analyzed the expression of a panel of common M1 (IL-1b, IL-12, iNOS, TNFα) and M2 (TGFβ, IL-10, ARG1) phenotype markers and the immune suppressive PD-L1 (CD274) in control and Pdpn-deleted BMDM co-cultivated with four different glioma cell lines." (PMID 30972297, 2019). "Specifically, we found that, as IGFBP5 levels increased, the expression of the seven immune checkpoint genes (BTLA, CD274, CTLA4, HAVCR2, LAG3, PDCD1, and PDCD1LG2) were increased and a large positive correlation was observed between IGFBP5 and these immune checkpoints in glioma." (PMID 38164271, 2024). "The immune checkpoints, including CD274 and PDCD1, were significantly differentially expressed between the two groups, and the TIDE score and exclusion score were significantly different between the two groups, which provides a preliminary basis for glioma immunotherapy." (PMID 36552760, 2022). "The immune checkpoints, including CD274 and PDCD1, were significantly differentially expressed between the two groups, and the TIDE score and exclusion score were significantly different between the two groups, which provides a preliminary basis for immunotherapy of glioma." (PMID 36552760, 2022). "Fortunately, the expression levels of PDCD1 (PD-1), CD274 (PD-L1), and CTLA4, the vital immune checkpoints in glioma, were significantly higher in IS2 than other subtypes, which indicated that patients receiving ICIs therapies might achieve a better curative effect." (PMID 34404444, 2021). "Moreover, the expression of Cd274 was well correlated with the respective expression of Ifng, Irf1, Gbp5, and Ccl2, demonstrating that selected IFN-γ-induced genes serve as feasible substitute indicators for IFN-γ level and thus might synergistically indicate the prognosis of glioma." (PMID 30333036, 2018).
glioma (continued). "Recent immune therapy targeting to the immune inhibitory checkpoint axis, i.e., programmed cell death protein 1 (PD-1) and its ligand PD-L1 (i.e., CD274 or B7-H1), has achieved breakthrough in many cancers but still not in glioma." (PMID 30687086, 2018). "Notably, IMPA2, SOD3, CD274, ITPRIPL1, and RAC2 displayed relatively negative correlations across multiple cancers, including glioma." (PMID 40852729, 2025). "Thus, we attempted to analyze certain immune checkpoints such as CD274 (PDL1), CD48, and HAVCR2 (TIM-3), which have been proven to play negative roles in gliomas." (PMID 40606983, 2025).
pancreatic cancer (713 papers, 2009 to 2026). "Further expression of PD-L1, a T-cell inhibitory receptor ligand causing immunosuppression, was upregulated in pancreatic cancer due to upregulation of H3K27me3 levels in CD274 promoter triggered by KMT2A overexpression." (PMID 34901003, 2021). "Verticillin A-mediated inhibition of MLL1 reduced H3K4me3 levels in the CD274 promoter and PD-L1 expression in tumor cells, coupled with anti-PD-1/PD-L1 antibody immunotherapy, effectively curtailed pancreatic tumor growth." (PMID 39080807, 2024). "Alongside LSD1, the H3K4 methyltransferase MLL1 promotes PD-L1 transcription by increasing H3K4me3 levels at the cd274 (PD-L1) promoter in pancreatic cancer cells." (PMID 39080807, 2024). "H3K4me3 is an 'activating' histone modifier in reflecting gene transcription and enriched with CD274 promoter in pancreatic cancer." (PMID 34088360, 2021). "The higher expression of MLL1 in pancreatic cancer enhances PD-L1(CD274) expression by increasing H3K4me3 status at the CD274 promoter region, thereby helping pancreatic cancer escape anti-PD-L1/PD-1 immunotherapy." (PMID 34201935, 2021). "Specifically, H3K4 trimethylation (H3K4me3) is enriched in the CD274 (PD-L1) promoter of pancreatic tumor cells." (PMID 32664564, 2020). "Silencing MLL1 expression dramatically decreases the H3K4me3 level in the CD274 promoter region, leading to a decreased PD-L1 mRNA in both human and mouse pancreatic cancer cells." (PMID 31258527, 2019). "Here, our data suggest that expression of CD274 in pancreatic cancer cells and the surrounding immunosuppressive MDSC is inhibited by miR-93 and 106b." (PMID 28423491, 2017). "Consistently, we found that medium conditioned by macrophages as the most abundant and pro-tumorigenic cell population in the tumor microenvironment, further enhanced CD274 expression in pancreatic cancer cells." (PMID 28423491, 2017). "Beyond the physical barrier, a recent study found that autophagy in CAFs promotes the “target loss” of CD274 through the IL6/USP14/CD274 signaling pathway, further contributing to the formation of an “immune desert” in pancreatic cancer, thereby enabling evasion from CD8+ T cell-mediated killing." (PMID 40733146, 2025). "In addition, cancer-associated fibroblast autophagy was shown to contribute to pancreatic cancer resistance to immune surveillance and caner immunotherapy through modulating CD274/PDL1 levels." (PMID 39403146, 2024). "In addition to HDACs, in a screening for epigenetic mechanisms that regulate PD-L1 expression in pancreatic cancer, histone methylation (H3K4me3) is evident to be enriched in the proximal CD274 promoter region both in vitro and in vivo." (PMID 31258527, 2019). "However, it significantly reduces the H3K4me3 level on cd274 promotor region in mouse pancreatic tumor cells." (PMID 29409480, 2018). "Similarly, analysis of the gene expression data from The Cancer Genome Atlas (TCGA) revealed a positive correlation of NR3C1 mRNA levels with CD274 (encoding PD-L1) mRNA levels and a moderate inverse correlation of NR3C1 mRNA levels with HLA-A mRNA levels in pancreatic cancer." (PMID 34873175, 2021). "In pancreatic cancer, inhibition of MLL1(KMT2A)activity or silencing expression reduces H3K4me3 levels in the CD274 promoter region and downregulates PD-L1 expression." (PMID 36713412, 2022). "To further investigate the relationship between PD-L1 and HAT1, we analyzed the mRNA levels of PD-L1 (CD274) and HAT1 in a subset of pancreatic cancer patients." (PMID 30709380, 2019). "Nonetheless, depletion of FAP+ CAFs in mice with pancreatic cancer enabled the antitumor efficacy of immune checkpoint blockade, namely anti-CTLA4 and anti-PD-L1 (CD274) antibodies." (PMID 29686035, 2018). "If THC inhibits CD274 (PD-L1) expression in HIV, similar to pancreatic cancer studies, then inhibition of PD-1/PD-L1 by marijuana might reverse HIV-mediated T cell exhaustion." (PMID 35642061, 2022).
pancreatic cancer (continued). "In pancreatic cancer, MLL1 protein could bind to the CD274 promoter to catalyze H3K4me3, leading to the increased expression of PD-L1." (PMID 33413496, 2021). "RNA-sequencing (RNA-seq) of pancreatic tumor lysates and principal component analysis revealed that KC;iASPPΔ8/Δ8 pancreata bear closer resemblance to KC than KPC pancreata and express greater Cd3, Cd4, Itgae, Pdcd1, Il10, Ccl5, Osm, and Cd274, reflective of an immunosuppressive stromal reaction." (PMID 36746936, 2023).
triple-negative breast carcinoma (705 papers, 2015 to 2026). An invasive breast carcinoma which is negative for expression of estrogen receptor (ER), progesterone receptor (PR), and human epidermal growth factor receptor 2 (HER2). "This also included the oncogene Janus kinase 2 (JAK2), which is co-amplified with CD274 (PD-L1) in classical Hodgkin lymphoma, triple negative breast cancer, and renal cell cancer as well as in NSCLC." (PMID 33576873, 2021). "For instance, in triple-negative breast cancer, Wnt/β-catenin signaling directly promotes the expression of CD274 (PD-L1)." (PMID 32560059, 2020). "Similarly, the PFS of patients with advanced triple-negative breast cancer treated with PDCD1/CD274 inhibitors combined with chemotherapy was longer than those treated with chemotherapy alone." (PMID 37988189, 2023). "CD28 within cancer cells also enhances PD-L1 expression by stabilizing CD274 mRNA through its interaction with SNRPB2, driving immune evasion in triple-negative breast cancer." (PMID 40303992, 2025). "For instance, in metastatic breast cancer, durvalumab did not significantly improve overall survival (OS) in the overall population but showed promise in triple-negative breast cancer (TNBC) patients, especially those with CD274 gain/amplification." (PMID 38713378, 2024).
bladder cancer (659 papers, 2013 to 2026). "Additionally, of the 24 TCGA cancer types, an inverse association between FOXA1 and CD274 gene expression was most significant in bladder cancer." (PMID 36323682, 2022). "In bladder cancer tissue elevated expression of immune checkpoint antigens such as programmed cell death protein-1 (PD-1; =CD279), its ligand, PD-L1 (=CD274), anti-cytotoxic T-lymphocyte associated antigen-4 (CTLA-4, =CD152), and B7-H3 (=CD276) was observed." (PMID 35563359, 2022). "A bladder cancer specific hypoxia signature previously published was used to assign hypoxia scores, which were then correlated with the expression of PD-L1 (CD274)." (PMID 34819027, 2021). "TMB (AUC = 0.73) and CD274 (AUC = 0.7) are predictive for ICB response in one bladder cancer cohort and one HNSC cohort, respectively." (PMID 34758832, 2021). "Programmed death ligand 1 (PD-L1, B7-H1, CD274) is expressed in several malignancies, including bladder cancer." (PMID 30400941, 2018). "The results revealed a significant positive correlation between CXCR6 expression and CD8A, effector T cell signature, and CD274 (PD-L1) in bladder cancer, suggesting that CXCR6 may hold potential as a predictive biomarker for immunotherapy response." (PMID 39588301, 2024). "Conversely, ectopic expression of FOXA1 in UM-UC-3 cells, a bladder cancer cell line with high basal PD-L1 expression, was sufficient to downregulate CD274/PD-L1 expression." (PMID 36323682, 2022). "Programmed cell death 1 (PD-1, also known as CD279), programmed cell death 1 ligand 1 (PD-L1, also known as CD274), and CTIL-4, are common immune checkpoints, have been described in bladder cancer." (PMID 33604353, 2020). "Programmed death ligand 1 (PD-L1, B7-H1, CD274) has been shown to be expressed in several malignancies, including bladder cancer." (PMID 30400941, 2018). "CD274 (PDL-1), CD68, CD16, and CD3 expression were observed in the bladder cancer tissues." (PMID 36732736, 2023). "Our data indicated that bladder cancer patients with high TstcSig exhibited “hot tumor” characteristics, characterized by a higher proportion of infiltrating immune cells, elevated immune scores, and increased expression of immune checkpoint genes such as PDCD1, CDLA4, LAG3, and CD274." (PMID 39033098, 2024). "For example, in the process of skin inflammation IFN-γ can induce the expression of CD274 mRNA in dermal fibroblast cells with NF-κB and MAPK and PI3K signaling pathways involved, and LPS-TLR4 interaction induces CD274 expression through MAPK pathways in bladder cancer cells." (PMID 23585913, 2013).
renal cell carcinoma (644 papers, 2008 to 2026). "Overexpression of CD274 (PD-L1) has been identified as a poor prognostic marker in many types of human cancers, including colon cancer and renal cell carcinoma." (PMID 34439934, 2021). "In summary, this data shows that miR-4429 targets CD274 and inhibits ccRCC proliferation, migration, and invasion by regulating PI3K/AKT signaling, thus potentially providing a promising therapeutic target and prognostic biomarker for renal cell carcinoma patients." (PMID 38802631, 2024).